TLR4 (toll like receptor 4)
Diseases named in the same sentence as TLR4 in open-access papers (continued):
Sharing a sentence is not in itself a finding about the gene and the disease.
autism (13 papers, 2013 to 2025). Persistent deficits in social interaction and communication and interaction as well as a markedly restricted repertoire of activity and interest as well as repetitive patterns of behavior. "One study using an autism mouse model found that increased gut permeability enabled LPS to reach the brain, triggering the TLR4/MyD88/NF-κB pathway and creating a pro-inflammatory environment." (PMID 40650125, 2025). "Our study provides the first experimental evidence that OT attenuates neuroinflammation in a VPA-induced autism rat model by modulating the microbiota-gut-brain axis through inhibition of TLR-4/IκB-α/NF-κB signaling pathway." (PMID 41001132, 2025). "Accumulating data had proven that the crosstalk between TLR4, NF-κB, and NLRP3 inflammasome is the keystone of the pathogenic events that occur in autism." (PMID 39596986, 2024). "A recent study revealed unusual elevations in TLR4 and NF-κB in the intestinal tracts of BTBR mice, suggesting the TLR4 signaling pathway as a viable target for treating autism-related gastrointestinal dysfunctions." (PMID 38741170, 2024). "Our findings reveal that the reintroduction of miR-137 mitigates autism-like behaviors by targeting TLR4, subsequently regulating microglial activation via the NF-κB signaling pathway." (PMID 38741170, 2024). "Utilizing BTBR mice as an autism model, the study demonstrated that intranasal administration of MSC-miR137-EVs ameliorates autism-like behaviors and inhibits pro-inflammatory factors via the TLR4/NF-κB pathway." (PMID 38741170, 2024). "One study showed that exposure to LPS activated the TLR4 signaling pathway and microglia in pregnant mice and led to autism-like behavior in the offspring." (PMID 37560531, 2023). "We investigated whether OT attenuates neuroinflammation in a valproic acid (VPA)-induced rat model of autism through the microbiota-gut-brain axis and the TLR-4/IκB-α/NF-κB signaling pathway." (PMID 41001132, 2025). "Agents that interfere with TLR4/NF-κB/NLRP3 inflammasome signaling in the hippocampal tissues were proven to significantly mitigate the neuroimmune dysregulation frequently encountered in autism." (PMID 39596986, 2024). "TLR4 has been shown to play a critical role in the maternal immune activation mouse model of autism, in which prenatal infection-induced activation of TLR4, and subsequent elevation of the key inflammatory cytokines IL6 and IL17α, are responsible for autistic-like behavior observed in pups." (PMID 29678176, 2018). "Thus, “leaky gut” could be a trigger for the development of autism via activation of the lipopolysaccharide-mediated TLR4–MyD88–NF-κB pathway." (PMID 36528850, 2023). "With this background in mind, to further elucidate the molecular mechanisms by which CV can ameliorate autistic disorder in this paper, C57BL mice were injected with valproic acid and treated for 40 days with 200 mg/kg of CV, and the TLR4/NF‐κB pathways were evaluated." (PMID 40462659, 2025). "Thus, in addition to research into mechanisms of autism-like behavior, BTBR mice can be used as a model of TLR3/TLR4-induced neuroinflammation and a unique model for finding and evaluating the effectiveness of various TLR antagonists aimed at reducing neuroinflammation." (PMID 36555219, 2022).
brain inflammation (13 papers, 2014 to 2025). "Human TLR4-activated astrocytes are implicated in the neuropathogenesis of many infectious and inflammatory diseases of the brain." (PMID 37511397, 2023). "Mechanistically, Listerin directly binds to Toll‐like receptor 4 (TLR4) mRNA and facilitates the IRE1α‐mediated cleavage and degradation of TLR4 mRNA, leading to the alleviation of TLR4‐induced brain inflammation." (PMID 40448625, 2025). "Given the link between gut dysbiosis and brain inflammation via the gut-brain axis, we examined key pro-inflammatory markers, including TLR4, TNF-a, and IL-1B." (PMID 41286043, 2025). "In both Naglu/Tlr4 and Naglu/Myd88 double-knockout mice, the onset of brain inflammation was delayed for several months when compared with MPS IIIB mice." (PMID 39497064, 2024). "The present study suggested that feeding with HFD under the intestinal deficiency of Jak3 caused brain induction of hypoxia inducible factor-1 as a mechanism of TLR4-activation-led brain inflammation." (PMID 36145091, 2022). "TLR2 activates the conduction cascade to amplify the inflammatory response, and TLR4 activates the upregulation of proinflammatory cytokines to trigger brain inflammation." (PMID 35401883, 2022). "Based on these findings, we suggest that TLR4 signaling-induced ER stress contribute to autonomic dysfunction and brain inflammation." (PMID 25811788, 2015). "HRT based on 17β-estradiol alone was devoid of anti-inflammatory properties in TLR4-induced brain inflammation." (PMID 24904290, 2014). "Together, these results indicated that alarmin HMGB1 mediates potentiation of LPS function, exacerbating TLR4-dependent systemic and brain inflammation in a rat PSI model and there is a positive-feedback loop between augmentation of LPS function by HMGB1 and subsequent HMGB1 release/serum." (PMID 29555931, 2018). "Once a positive correlation between SAA1 serum levels and TLR4 mRNA with significant predictive value for severity and patient outcome was established, we explored the role of SAA1 in brain inflammation." (PMID 34070533, 2021). "Furthermore, blockade of ER stress attenuates LPS-induced neuroinflammation and TLR4 expression in the PVN, demonstrating a possible role for TLR4-induced brain inflammation and ER stress in autonomic dysfunction." (PMID 25811788, 2015). "Among these, anti-TLR2 and -TLR4 neutralizing antibodies may be considered an interesting approach to block peripheral TLR-mediated inflammation, despite they have no inhibitory effect on brain inflammation." (PMID 36460875, 2023).
campylobacteriosis (13 papers, 2012 to 2024). Infections with bacteria of the genus campylobacter. "It is well known that the immunopathological sequelae during campylobacteriosis are caused by TLR-4-dependent host immune responses that are induced by LOS derived from the bacterial cell wall." (PMID 33255723, 2020). "The immunopathological sequelae of campylobacteriosis are caused by Toll-like Receptor-4 (TLR4)-dependent host immune responses, induced by bacterial lipooligosaccharide (LOS)." (PMID 32443576, 2020). "The immunopathological impact of TLR-4 dependent signaling of lipooligosaccharide in human campylobacteriosis is even more underlined by the fact that humans are up to 1000 times more sensitive to TLR-4 ligands than rodents." (PMID 22808254, 2012). "Given that the LOS of C. jejuni targets the toll-like receptor 4 (TLR4), the major role of LOS in the induction and progress of campylobacteriosis was supported by the fact that C. jejuni infection induced significantly milder enterocolitis symptoms in TLR4-deficient mice." (PMID 33935732, 2021). "Given that C. jejuni-induced enterocolitis is mainly due to TLR-4-mediated sensing of the pathogenic LOS, the TLR-4 antagonistic effects of carvacrol constitutes an important molecular mechanism underlying the disease-alleviating effects of the phenolic compound in campylobacteriosis." (PMID 36830689, 2023). "A key mechanism of C. jejuni-induced immunopathology during acute campylobacteriosis in infected secondary abiotic IL-10-/- mice is the induction of the TLR-4 dependent signaling cascade by bacterial cell wall-derived LOS." (PMID 34070612, 2021). "Independent from TLR4, C. coli and E. coli stably colonized the gastrointestinal tract, but only C. coli induced clinical signs of campylobacteriosis." (PMID 33261211, 2020). "This confirms that C. coli induces campylobacteriosis similar to C. jejuni in a TLR4-dependent manner and that LOS plays a major role in C. coli immunopathogenesis." (PMID 33261211, 2020). "The pathogenesis of acute human campylobacteriosis is strongly triggered by the activation of innate immune responses via Toll-like Receptor-4 (TLR-4) mediated sensing of the bacterial lipooligosaccharide (LOS) that is expressed on the surface of C. jejuni." (PMID 31921356, 2020). "Overly activated innate immunity reduced the colonization resistance of animals without TLR4(−/−) deficiency, which created conditions for the development of campylobacteriosis." (PMID 39766533, 2024). "In conclusion, our study provides evidence that TLR4 is involved in mediating C. coli-LOS-induced immune responses in intestinal and extra-intestinal compartments during murine campylobacteriosis." (PMID 33261211, 2020). "Taken together, these results confirm the down-regulation of TLR-4 signaling by NOD2 activation not only in IBD, but also in campylobacteriosis." (PMID 32231139, 2020). "Additionally, these results prove that TLR-4 dependent LOS signaling is essential for C. jejuni-induced intestinal immunopathology in mice and that innate immune responses represent hallmarks in the immunopathogenesis of campylobacteriosis." (PMID 32231139, 2020). "Therefore, we analyzed C. coli-induced campylobacteriosis in secondary abiotic IL-10−/− mice with and without TLR4." (PMID 33261211, 2020).
coronary atherosclerosis (13 papers, 2011 to 2025). Atherosclerosis of the coronary vasculature. "Plasma EV-lnc-MRGPRF-6:1 upregulation promotes macrophage M1 polarization and inflammation in coronary atherosclerosis patients by activating toll-like receptor-4, myeloid differentiation factor-88, and mitogen-activated protein kinases (TLR4-MyD88-MAPK)." (PMID 37237557, 2023). "A previous study found that the expression of TLR4-positive circulating monocytes increased in patients with acute coronary syndrome and coronary atherosclerosis compared with the control group." (PMID 33728029, 2021). "Myocardial PAR1 expression strongly correlated with TLR2 and TLR4 in patients with coronary atherosclerosis." (PMID 34944024, 2021). "TLR4 was expressed on the membranes of macrophages that promoted proinflammatory signaling and played a key role in the development of coronary atherosclerosis." (PMID 31780868, 2019). "TLR4 was a pathophysiological link between inflammatory response and coronary atherosclerosis." (PMID 35425840, 2022). "In patients with coronary atherosclerosis, deletion of RFX1 activates TLR4 and is involved in disease progression through histone modifications that further activate CD14+ monocytes." (PMID 41425715, 2025). "In patients with coronary atherosclerosis, EVs carrying lncRNA-MRGPRF-6:1 promote M1 macrophage polarization by activating TLR4, myeloid differentiation factor-8, and mitogen-activated protein kinase (TLR4-MyD88-MAPK)." (PMID 38260141, 2023). "Toll-like receptor 4 (TLR4) activation promoted inflammatory response and oxidative stress and was involved in regulating proinflammatory cytokine TNF-α through its key role in coronary atherosclerosis." (PMID 31780868, 2019). "This study also suggested that dysregulation of miR-146a/b expression may contribute to prolonging the activation of Toll-like receptor 4 (TLR4) which, in turn, may induce miR-146a/b expression as a negative regulator and, so, induce progression of coronary atherosclerosis in patients with CAD." (PMID 25013816, 2014).
gastritis (13 papers, 2013 to 2025). Inflammation of the stomach. "Accordingly, a study revealed that blocking TLR4 in a mouse model led to a higher bacterial load and higher gastritis score but significantly lower levels of the Th1-associated cytokine IL-12 upon H. pylori infection." (PMID 32486097, 2020). "The Thr399Ile polymorphism in TLR4 was also identified as a genetic risk factor for gastritis and pre-cancerous lesions in a northern Indian population." (PMID 24959291, 2014). "Lm-ME suppressed the activation of TAK1 in both LPS/TLR4-activated macrophages and in HCl/EtOH-induced gastritis symptom, so it is possible that the observed downregulation of IKKα/β resulted from both Src and TAK1 inhibition." (PMID 31611922, 2019). "The grade of gastritis in the TLR4-blocked H. pylori infection group was significantly lower than that in the non-blocked H. pylori infection group (P<0.05)." (PMID 26901645, 2016). "The mean optical density of TLR4 staining in patients with H.pylori-induced gastritis was significantly higher than that in normal controls." (PMID 23437218, 2013). "The study results showed that TNF-α, IL-1β, IL-6, TLR4, and MBL2 are common among Covid-19, IBD, gastritis, and diarrhea." (PMID 35845309, 2022). "For instance, H. pylori–induced gastritis patients showed higher expressions of TLR2, TLR4, and TNF–α in their gastric biopsies of while metaplasia and dysplasia patient samples exhibited higher TLR2 expression." (PMID 36317079, 2022). "To determine H. pylori infection generated gastritis in the gastric mucosa with TLR4 or CD25 blockage following infection, we measured the grades of gastritis in the gastric mucosa." (PMID 26901645, 2016). "While TLR2, TLR4, TLR5, and TLR9 appear to be important for H. pylori recognition, their role in the evolution of gastritis to more advanced lesions remains unclear." (PMID 25101079, 2014). "Immunohistochemical analysis for TLR4 was performed on paraffin sections of antral biopsy specimens obtained from 15 patients with H.pylori-induced gastritis and 8 H.pylori-negative controls." (PMID 23437218, 2013). "The expression levels of TLR4 mRNA were also increased in gastric mucosa specimens with H.pylori-induced gastritis than in H.pylori-negative controls." (PMID 23437218, 2013). "After H. pylori infection, the grade of gastritis was significantly different among the different groups (P = 0.000), and was not significantly different between the control group in which TLR4 was blocked and the control group in which TL4 was not blocked (P>0.05)." (PMID 26901645, 2016). "In the TLR4-blocked H. pylori infection group, the grade of gastritis was significantly higher than that in the control group regardless of whether or not TLR4 was blocked (P<0.05–0.001)." (PMID 26901645, 2016). "Using confocal microscopy, TLR4, TLR5 and TLR9 have been observed in the antrum and corpus of the stomach samples from patients with H. pylori-related gastritis and with non-inflamed gastric mucosa." (PMID 40362298, 2025).
Hyperinsulinemia (13 papers, 2011 to 2025). An increased concentration of insulin in the blood. "At the organism level, the loss-of-function mutation in TLR4 partially protected against HFD-induced hyperinsulinemia and impaired glucose tolerance." (PMID 26539824, 2015). "By enhancing PI3K/AKT signaling, GLP-1RAs restore insulin sensitivity, mitigate hyperinsulinemia, and suppress inflammatory pathways (NF-κB, TLR4)." (PMID 41403736, 2025). "Overall, the current study has presented the novel finding that negative regulation of TLR4 expression exists in the heart during hyperinsulinemia using an integrative approach, including a unique, large animal model." (PMID 25101057, 2014). "Additionally, LPS binds to Toll-like receptor 4 (TLR4), further amplifying inflammation and hyperinsulinemia." (PMID 40842497, 2025). "This is consistent with previous studies suggesting that LPS might be involved in glucose-induced hyperinsulinemia, possibly via activation of toll-like receptor 4 (TLR4)." (PMID 35055664, 2022). "Therefore, our findings suggested that prolonged hyperinsulinemia induces impairment in TLR4 protein expression and/or translocation to the plasma membrane." (PMID 25101057, 2014). "The failure of membrane-rich GLUT4 expression to respond to reduced TLR4 expression secondary to hyperinsulinemia in the current study could suggest that TLR4 signaling does not primarily regulate glucose transport in the myocardium in contrast to the skeletal muscle." (PMID 25101057, 2014). "Markers of cardiac TLR4 signaling and GLUT expression were not affected by hyperinsulinemia and concomitant TLR4 down-regulation." (PMID 25101057, 2014). "While bone-marrow transplant studies indicate that TLR4 in the hematopoietic system opposed to the non-hematopoietic system may be responsible for TLR4 mediated IR during HFD wherein TLR4 chimeric mice exhibit reduced hyperinsulinemia, hepatic, and WAT IR." (PMID 23675368, 2013). "The down-regulation of TLR4 combined with the lack of increased production of pro-inflammatory cytokines (i.e., IL-6 and TNF-α) and SOCS3 following insulin infusion in the current study suggested that hyperinsulinemia exerts an anti-inflammatory effect on the heart in non-obese individuals." (PMID 25101057, 2014).
intestinal inflammation (13 papers, 2011 to 2025). "Furthermore, we found that loss of the C. jejuni capsule led to increased TLR4 activation and exaggerated inflammation and gastroenteritis." (PMID 25033044, 2014). "Moreover, it was previously shown that strains of C. jejuni with modifications of LPS that promote inflammatory reactions are associated with elevated severity of gastroenteritis, suggesting a leading role for TLR4 in activation of innate immunity in response to this pathogen." (PMID 29535976, 2018). "In contrast to the modest responses seen in infected Tlr4−/−/Sigirr−/− mice, when we infected Tlr2−/−/Sigirr−/− mice, we observed a significantly exaggerated and accelerated form of gastroenteritis, especially at the early stages of infection (3 DPI)." (PMID 25033044, 2014). "Previous studies confirmed that BBR could protect islet beta cells in DM, and also prevent intestinal inflammation in bowel disease through depressing TLR4 signaling pathways." (PMID 28217099, 2017). "Although the Tlr4−/−/Sigirr−/− mice were heavily colonized by C. jejuni, they proved largely unresponsive to the pathogen, exhibiting few if any signs of the gastroenteritis seen in infected Sigirr−/− mice." (PMID 25033044, 2014). "Moreover, TLR4 has been identified as being a major driver of inflammation in C. jejuni-infected IL-10−/− mice and the present study found the gastroenteritis seen in infected Sigirr−/− mice is almost completely TLR4 dependent." (PMID 25033044, 2014). "Accordingly, dietary OA can restore the gut microbial balance and elevate SCFAs production to inhibit the TLR4/NF-κB signaling pathway and ameliorate HSD stress-induced intestinal inflammation in broilers." (PMID 36372893, 2022). "This study demonstrates that TLR2, TLR4, TLR8, and TLR9 expression increases in active UC patients, and that the mRNA levels positively correlate with the severity of intestinal inflammation as well as with inflammatory cytokines." (PMID 22185629, 2011).